GATA3 (GATA binding protein 3)
Diseases named in the same sentence as GATA3 in open-access papers (continued):
Sharing a sentence is not in itself a finding about the gene and the disease.
Barakat syndrome (10 papers, 2013 to 2025). "One recent case report from 2023 identified Barakat syndrome in a patient with a GATA3:c.916C > T nonsense mutation on chromosome 10p14." (PMID 41019281, 2025). "Barakat syndrome is usually caused by a mutation or knockout in GATA3, a zinc finger protein found on chromosome 10p14 which plays a role in embryologic formation of the central nervous system, thymus, auditory apparatus, kidney, and parathyroid glands." (PMID 41019281, 2025). "Gata3-deficient mice display sensorineural hearing phenotypes, similar to those in patients with HDR syndrome." (PMID 38353121, 2024). "In humans, GATA3 mutations lead to HDR syndrome with variable phenotypes, likely resulting from developmental defects similar to those observed in mouse mutants." (PMID 38353121, 2024). "Our case of Barakat syndrome is an excellent example of the phenotypic variability of heterozygous GATA3 variants." (PMID 38116790, 2023). "GATA3 haploinsufficiency due to loss‐of‐function mutations or deletions is the known pathogenic mechanism causing HDR syndrome." (PMID 32155322, 2020). "Barakat syndrome is an autosomal dominant rare genetic disease caused by haploinsufficiency of the GATA binding protein 3 (GATA3) gene." (PMID 31660939, 2019). "This is the first report of a heterozygous GATA3 whole gene deletion causing HDR syndrome in a Sri Lankan family." (PMID 31660939, 2019). "Herein, we describe the first report of a heterozygous GATA3 whole gene deletion causing HDR syndrome in a Sri Lankan family." (PMID 31660939, 2019). "Although the relationship between GATA3 and inner ear development has been studied, a case of HDR syndrome with sensorineural deafness mimicking an X-linked stapes gusher has not previously been reported." (PMID 29073906, 2017). "HDR syndrome is primarily caused by variants in the GATA3 gene, located on chromosome 10p (10p14)." (PMID 38116790, 2023). "Taken together, these findings indicate that these genes may act as downstream genes of Gata3 in cochlear SCs and that the altered expression levels of these genes may contribute to Gata3 deficiency-induced sensorineural deafness in HDR syndrome." (PMID 34349220, 2021). "HDR syndrome is a rare autosomal dominant genetic disorder with variable expressivity and penetrance caused by haploinsufficiency of the GATA binding protein 3 (GATA3) gene (OMIM#131320) on chromosome 10p14." (PMID 31660939, 2019). "GATA3 is defective in the Barakat syndrome, a disorder that includes sensorineural deafness." (PMID 36999169, 2023). "Barakat syndrome is phenotypically identified with different combinations of the ‘HDR’ triad with or without heterozygous GATA3 gene variants." (PMID 38116790, 2023). "Although the initial suspected diagnosis was Alport syndrome, the presence of the heterozygous GATA3 whole gene deletion increased the possibility of Barakat syndrome, and the lack of ocular abnormalities and hematuria made Alport syndrome less likely." (PMID 41019281, 2025).
neuroendocrine tumors (10 papers, 2017 to 2025). "In addition, its expression GATA-3 has also been detected in a variety of cancers, including neuroendocrine tumors." (PMID 40777117, 2025). "Additionally, the transcription factor GATA3 is useful in identifying PPGLs and excluding other neuroendocrine neoplasms." (PMID 35205664, 2022). "Neuroendocrine tumors, including small cell lung cancer and Merkel cell carcinoma, showed no cases with GATA3 expression." (PMID 37629741, 2023). "Also, GATA3 expression is typically found in the majority of PGL but not in neuroendocrine tumors, making it a valuable marker for differentiation." (PMID 39507200, 2024). "Additionally, neuroendocrine tumors in pancreas, including low-grade tumors, such as carcinoids and well-differentiated pancreatic neuroendocrine tumors were negative for GATA3." (PMID 28693516, 2017).
ulcerative colitis (10 papers, 2014 to 2025). An inflammatory bowel disease involving the mucosal surface of the large intestine and rectum. "In a recent study, a GATA3-specific DNAzyme (hgd40) was used to inhibit GATA3, which resulted in successfully protecting mice from chronic inflammation caused by ulcerative colitis." (PMID 32850359, 2020). "Chronic overexpression of GATA binding protein 3 (GATA3) can lead to the development of ulcerative colitis, thus making GATA3 a common pharmaceutical target for the treatment of IBD." (PMID 39457699, 2024). "Hypermethylation is not restricted to cancer since recent studies demonstrated that the GATA3 gene was also hypermethylated in ulcerative colitis." (PMID 28969068, 2017). "In contrast, initiation of IL-4 transcription in naïve T cells is regulated by GATA3; and the expression of GATA3 is significantly increased in the bowel mucosae of children with the inflammatory bowel disease, ulcerative colitis." (PMID 28498822, 2017). "In ulcerative colitis (UC) 5 genes (CXCL14, CXCL5, GATA3, IL17C, and IL4R) were hypermethylated compared to healthy controls." (PMID 25526479, 2014).
adenoma (9 papers, 2013 to 2025). A neoplasm arising from the epithelium. "Further investigation with IHC for GATA2, GATA3 and alpha subunit would help the differentiation between true null cell adenomas and gonadotroph adenomas and thus provide the true prevalence of null cell adenomas." (PMID 34589436, 2021). "Our results contradict a previous study that documented the highest GATA3 expression in canine mixed carcinoma, with the lowest level in a complex adenoma." (PMID 32225066, 2020). "The transcription factor GATA3 had its highest levels in mixed carcinoma samples and its lowest levels in complex adenoma." (PMID 28945747, 2017). "Importantly, the null cell adenomas according to the old 2004 WHO classification are now almost entirely assigned to the gonadotroph group (SF-1 positive or GATA3 and ERα)." (PMID 40579705, 2025). "However, silencing of the GATA3 locus is not sufficient to promote malignant progression, since premature loss of GATA3 expression in well-differentiated adenomas promotes widespread detachment of cells from the basement membrane followed by apoptosis." (PMID 25479686, 2014).
allergic rhinitis (9 papers, 2011 to 2025). Inflammation of the nasal mucous membranes caused by an IgE-mediated response to external allergens. "In another research, AS-IV attenuates the symptoms of ovalbumin-induced allergic rhinitis via regulating the expression levels of GATA binding protein 3, forkhead box protein 3, and T cells." (PMID 34482800, 2021). "GATA3, one of our most-enriched TFs at lncRNA promoters and an essential regulator of type 2 helper T-cell (Th2) cytokine production, is itself cis-regulated by an antisense lncRNA (GATA3-AS1), which is increased in patients with allergic rhinitis, a Th2-associated disease." (PMID 25275320, 2014). "Although a positive correlation was found between GATA-3+ cells and GM-CSF+ cells in the nasal mucosa of patients with allergic rhinitis, there is no study to our knowledge that directly analyzes the role of GATA-3 in GM-CSF production." (PMID 25838639, 2015). "However, the percentage of GATA3+ T cells are significantly higher in allergic nasal mucosa than those in nonallergic nasal mucosa (allergic rhinitis: 3.9 ± 1.8%, nonallergic rhinitis 1.1 ± 0.6%, P = 0.003)." (PMID 22164170, 2011).
glioma (9 papers, 2016 to 2024). A benign or malignant brain and spinal cord tumor that arises from glial cells (astrocytes, oligodendrocytes, ependymal cells). "Therefore, TIMM44 downregulation in YME1L-deficient glioma cells should be caused by shutdown of GATA3-dependent TIMM44 transcriptional machinery following mitochondrial stress." (PMID 36438483, 2022). "TIMM44 upregulation in glioma is possibly due to increased TIMM44 transcriptional machinery by the transcription factor GATA3 in a YME1L (YME1 Like 1 ATPase)-dependent manner." (PMID 36438483, 2022). "Importantly, GATA3 chromosome immunoprecipitation (ChIP) results demonstrated that GATA3-TIMM44 promoter binding in P1 glioma cells was robustly decreased after YME1L silencing or depletion." (PMID 36438483, 2022). "Upregulation of TIMM44 in glioma could be due to increased TIMM44 transcriptional machinery through GATA3." (PMID 36438483, 2022). "Therefore, YME1L promoted GATA3-dependent TIMM44 transcription in glioma cells." (PMID 36438483, 2022). "Thus, a reduction of GATA3 expression may be involved in CXCL16-regulated or CX3CL1-regulated inhibition of THSD4 expression in gliomas." (PMID 32346064, 2020). "shRNA-induced silencing of GATA3 significantly decreased TIMM44 mRNA and protein expression in P1 glioma cells, and YME1L expression was unchanged." (PMID 36438483, 2022). "Moreover, overexpression of YME1L, by the lentiviral YME1L-expressing construct (“+OE-YME1L”), failed to restore TIMM44 mRNA expression in GATA3-silenced P1 glioma cells." (PMID 36438483, 2022).
pheochromocytoma (9 papers, 2017 to 2025). "For immunohistochemistry analysis, positivity for tyrosine hydroxylase and GATA3 confirmed the diagnosis of pheochromocytoma." (PMID 35304467, 2022). "In addition, it is worth noting that GATA-3, a protein commonly used to label cells of breast origin, is also expressed in pheochromocytoma cells, which may confuse the diagnosis." (PMID 31109373, 2019). "Pheochromocytomas and abdominal paragangliomas stain positive for neuroendocrine markers CgA, SYP, ISL1, INSM1 and, often, GATA3; subsets of cases may display an intricate network of supporting sustentacular cells which are highlighted by an S100 or SOX10 stain." (PMID 37685605, 2023). "Immunohistochemistry demonstrated that the pheochromocytoma cells were positive for chromogranin A (CgA) and synaptophysin (SYN), and negative for cytokeratin (CK), GATA3, and ER (-, 5)." (PMID 40746928, 2025).
prostatic adenocarcinoma (9 papers, 2017 to 2025). "In descending order of importance to distinguish from prostate adenocarcinomas, genes for uroplakin II, S100P, GATA3 and thrombomodulin had high discriminant loadings (> 0.3)." (PMID 33762601, 2021). "Secondary EMPD caused by prostatic adenocarcinoma can be distinguished from primary EMPD by p501S (prostein) and GATA3." (PMID 28693610, 2017). "Furthermore, another study reported the specificity of GATA3 in prostate adenocarcinoma (PAC) was 15.2%, while in UC was 100%." (PMID 38161907, 2023). "In addition, prostatic adenocarcinoma was positive for GATA3 in 2% of the cases." (PMID 37629741, 2023). "Prostatic adenocarcinoma is positive for p501S but negative for GATA3 whereas EMPD shows an opposite profile." (PMID 28693610, 2017). "Sensitivity for diagnosing prostate adenocarcinoma with PSA level and NKX3.1 are nearly 100% and 88.3%, respectively, whereas CK34βE12, p63 and GATA3 are not usually present in prostatic adenocarcinoma (1.8%, 0% and 0%, respectively, in prostatic adenocarcinoma tissue)." (PMID 41585080, 2025). "Additionally, while PSA negativity is atypical for prostate adenocarcinoma, the absence of GATA3, a marker of urothelial origin, along with the positive AMACR, supported a diagnosis of prostatic ductal adenocarcinoma." (PMID 40662003, 2025).
renal cell carcinoma (9 papers, 2016 to 2025). "GATA3 is expressed in a subset of renal cell carcinomas, particularly ChRCC with sarcomatoid differentiation." (PMID 40691018, 2025). "A previous report showed that among renal cell carcinomas, chromophobe had 51% GATA3 expression, and the remaining subtypes had 2% expression." (PMID 37629741, 2023). "This GATA3 CpG island was differentially methylated in renal cell carcinoma and thyroid adenocarcinoma." (PMID 27658391, 2016). "The GATA3 expression suggested sarcomatoid urothelial carcinoma, although the awareness of GATA3 expression in a subset of renal cell carcinomas and high‐grade sarcomas led to including sarcomatoid renal cell carcinoma and sarcoma in the differential diagnosis." (PMID 40691018, 2025). "Moreover, several other cancers exhibited aberrant GATA3 expression, including urothelial carcinoma, renal cell carcinoma, pancreatic cancer, cervical cancer, or Hodgkinʼs lymphoma." (PMID 27658391, 2016). "As for the distal tubular markers such as GATA3 and parvalbumin, none of the MiT family translocation renal cell carcinomas retrieved was positive for the former." (PMID 35980471, 2022). "Tumor cells were diffusely positive for CK7, EMA, and inhibin, while they were negative for CK20, P63, CK 5/6, CD10, renal cell carcinoma (RCC), TTF1, PAX8, CEA, and GATA3." (PMID 37261186, 2023).
rheumatoid arthritis (9 papers, 2014 to 2025). A chronic, systemic autoimmune disorder characterized by inflammation in the synovial membranes and articular surfaces. "Additionally, we report association of GATA3 variants with AAD: this adds to the recent report of association of GATA3 variants with rheumatoid arthritis." (PMID 24614117, 2014). "For instance, nicotine treatment significantly increases Th2 differentiation in peripheral blood mononuclear cells (PBMCs) isolated from rheumatoid arthritis patients, as observed by an increase in IL-4 production and enhanced GATA3 expression." (PMID 35003121, 2021). "The presence of these pathways in human disease is confirmed by detection of GATA3-positive cells and eosinophils in the joints of rheumatoid arthritis patients." (PMID 27273006, 2016). "Activating CAP with nicotine reduced the expression of Th17-related IL-17 and Ror-γ, increased expression of Th2-related IL-4 and Gata3, and attenuated the inflammatory response in a murine collagen-induced arthritis (CIA) model of rheumatoid arthritis." (PMID 33380272, 2021).
serous ovarian carcinoma (9 papers, 2020 to 2025). "GATA3 expression promotes proliferation and migration in high‐grade serous ovarian cancer, and is associated with a poor prognosis of high‐grade serous ovarian cancer." (PMID 36468944, 2023). "In high-grade serous ovarian cancer, GATA3 acts as an oncogenic protein and high expression of GATA3 is associated with poor prognosis in patients." (PMID 34399777, 2021). "Importantly, GATA3 acts as an oncogenic protein and high expression of GATA3 is associated with poor prognosis in patients with high-grade serous ovarian cancer." (PMID 34399777, 2021). "Based on the results of this study, GATA3 expression was observed in 6 out of 89 cases of endometrial adenocarcinoma (7%) and 4 out of 73 cases of ovarian serous carcinoma (6%)." (PMID 39118796, 2024). "There is a close relationship between GATA3 and poor prognosis of high-grade serous ovarian carcinoma." (PMID 34109184, 2021). "In a follow-up study performed in USA, GATA3 enhances the stemness of tumor cells and promotes the proliferation and migration of serous ovarian cancer cells." (PMID 34399777, 2021). "Moreover, it was showed that GATA3 expression is related to poor prognosis of high-grade serous ovarian carcinoma patients." (PMID 33907495, 2021). "Likewise, GATA3 also promoted the proliferation and invasion of high-serous ovarian cancer cells by regulating M2-type macrophage polarization." (PMID 32538432, 2020). "GATA-binding protein 3 (GATA3), secreted primarily by TAMs in high-grade serous ovarian cancer, promotes tumor progression, angiogenesis, and chemotherapy resistance." (PMID 40136652, 2025). "Our results showed that only 2.4% of ovarian serous carcinomas had focal MGP expression, which is lower than the reported positivity of GATA3 (~6%,) and TRPS1 (14%,)." (PMID 36284362, 2022).
Arthritis (8 papers, 2012 to 2023). Inflammation of a joint. "Our research expands the phenotypic spectrum for GATA3 mutations and presents a possible genetic cause for this patient’s arthritis." (PMID 31238969, 2019). "One study showed that increased GATA-binding protein 3 (GATA3) expression protects against joint inflammation and also reduces Th17 cell differentiation during experimental arthritis." (PMID 33805933, 2021). "The gene expression levels of IL-4 and the Th2 cell transcription factor Gata3 were significantly higher in the pLACK- and rLACK-treated or -vaccinated groups than in the control arthritis group." (PMID 30013572, 2018). "In the present study, we demonstrated for the first time that IL-18-expressing plasmid gene combined with IL-4 skewed the balance of Th1/Th2/Th17 to a Th2 type and increased GATA-3 and Foxp3 expression on collagen-induced arthritis." (PMID 29854762, 2018). "Taken together, our experiments demonstrate that a saturated LCFA induced RIDD-mediated t-bet and gata-3 mRNA degradation in iNKT cells, thereby suppressing arthritis." (PMID 29097726, 2017). "Mice that overexpress GATA3 are protected from joint inflammation in a model of arthritis." (PMID 31238969, 2019). "When Exo-FBS or Exo-RA was administered to the collagen-induced arthritis model, serum interleukin (IL)-4 and the proportion of Th2 (CD4+CD25+GATA3+) and M2 (CD11c − CD206+ of CD45+CD64+) cells were significantly increased compared to the control group." (PMID 37794417, 2023). "Our findings indicate that pIL-18 gene combined with IL-4 ameliorates arthritis in the CIA mouse by suppression of Th1 and Th17 cytokines and increasing expression of FoxP3 and GATA-3." (PMID 29854762, 2018). "Our previous report showed that combined treatment of low-dose IL-18 with IL-10 can prevent the progression of arthritis in CIA mice and that this is mediated by a GATA-3-dependent mechanism." (PMID 29854762, 2018). "FOXP3 (Treg) and GATA3 (Th2) mRNA expression levels were not significantly different between the SCW-arthritis groups." (PMID 22719976, 2012).
bladder urothelial carcinoma (8 papers, 2021 to 2025). "Consequently, GATA3 immunohistochemistry (IHC) is frequently utilized in diagnostic surgical pathology to differentiate primary or metastatic urothelial bladder cancer (UBC) from morphologic duplicates." (PMID 39979991, 2025). "We aimed to assess the impact of GATA3 binding protein (GATA3) gene copy number alterations on tumor aggressiveness, patient prognosis, and GATA3 protein expression in a large urothelial bladder cancer cohort." (PMID 39979991, 2025). "High-level GATA3 amplification is common in urothelial bladder cancer and correlates with grade progression in pTa tumors, while GATA3 deletion is rare." (PMID 39979991, 2025). "GATA3 staining aided in the diagnosis of urothelial bladder cancer with left supraclavicular node metastasis." (PMID 35078521, 2022). "GATA3, known as a specific marker of bladder urothelial carcinoma, is significantly highly expressed in BLCA." (PMID 35647011, 2022). "In descending order of importance for the urothelial lineage gene expressions, UKP2, S100P, GATA3 and THBD were the most important predictors for bladder urothelial carcinoma based on the discriminant loading > 0.3." (PMID 33762601, 2021). "NanoString-based gene expression analysis using typically luminal (GATA3+/KRT20+) and basal markers (KRT14+/KRT5+/GATA3low/-/KRT20low/-) classified urothelial bladder carcinoma samples as luminal, basal, and a third category (KRT14-/KRT5-/GATA3-/KRT20-), null/double negative (non-luminal/non-basal)." (PMID 34771663, 2021).